BAD (BCL2 associated agonist of cell death)
Diseases named in the same sentence as BAD in open-access papers (continued):
Sharing a sentence is not in itself a finding about the gene and the disease.
ovarian carcinoma (15 papers, 2007 to 2022). A malignant neoplasm originating from the surface ovarian epithelium. "The substrates of CN, including c-Jun, DAXX, BAD, Rb and Drp1, were associated with the prognosis in ovarian cancer." (PMID 31399054, 2019). "After CREB knockdown, expression of apoptosis associated molecules (Apaf-1, BAD and cleaved caspase 7) were found upregulated in ovarian cancer cells as compared to NC shRNA treated cells." (PMID 28881798, 2017). "We previously developed a BAD-mediated apoptotic pathway gene expression signature using PCA that summarized the overall expression of the BAD pathway and found that the expression of the BAD pathway was associated with the development of ovarian cancer chemoresistance." (PMID 25653146, 2015). "The RAS/MEK/ERK and PI3K/AKT/mTOR signaling cascades converging at BAD participate in maintaining cell survival following both cisplatin and paclitaxel treatment in ovarian cancer." (PMID 35791346, 2022). "Under stress conditions, BCL2A1 accumulated and colocalized with mitochondria to suppress intrinsic cell apoptosis by interacting with the BH3-only subfamily BCL2 members HRK/BAD/BID in ovarian cancer cells." (PMID 34572804, 2021). "Seventh, there are terms “Activation of BAD and translocation to mitochondria” and “Signaling by Hippo” as the mechanisms involved in cancer and the surrounding normal cells for signaling for ovarian cancer survival." (PMID 33228226, 2020). "Cisplatin-induced cytotoxicity caused the phosphorylation of BAD at ser-112 via Erk and BAD at ser-136 via PI3K/Akt, whose block sensitized ovarian cancer cells to cisplatin." (PMID 28938696, 2017). "The normal ovary samples (n=28) had a mean BAD-mediated apoptotic pathway expression score of 8.1968, whereas the ovarian cancer samples (n=78) had a mean score of −2.9424 (P<0.001)." (PMID 25653146, 2015). "Evidence suggests that the expression levels of the BAD-mediated apoptotic pathway and BAD protein influence endometrial and ovarian cancer cell resistance to chemotherapy." (PMID 25653146, 2015). "Another report showed that cisplatin-induced DNA damage causes the phosphorylation of BAD Ser-136 via a PI3K/Akt cascade and that inhibition of either of these cascades sensitizes ovarian cancer cells to cisplatin." (PMID 19384426, 2007). "The risk model composed of GSK3α/β, HSP70, MEK1, MTOR, BAD, and NDRG1 could predict survival prognosis of ovarian cancer patients efficiently and help disease management." (PMID 35840928, 2022). "PIM2 is also induced by cisplatin in ovarian cancer cells, and the targeting of the PIM2 kinase by biochemical inhibitors or RNA interference leads to the reduction of cell growth, the decrease of BAD phosphorylation, and the sensitization of the ovarian cancer cells to drug-induced apoptosis." (PMID 33854618, 2021). "The range of PP2C expression was wider in the ovarian cancer samples than in the normal ovary samples, thus suggesting that additional factors may influence the phosphorylation status of BAD and thus the potential for oncogenesis." (PMID 25653146, 2015). "Furthermore, we demonstrated that PP2C, a BAD phosphatase at Ser-155, is expressed at a higher level in normal ovaries than in ovarian cancers." (PMID 25653146, 2015). "Therefore, it is reasonable to hypothesize that EGFR overexpression in artesunate-resistant ovarian cancer cells could impair the ability of artesunate to induce apoptosis through the BAD/Bcl-xL complex." (PMID 33652561, 2021). "Furthermore, we have previously demonstrated that ovarian cancer samples from patients categorized as incomplete responders to primary platinum therapy have a decreased expression of the BAD protein Ser-155 phosphatase, PP2C, compared to samples from patients categorized as complete responders." (PMID 25653146, 2015).
ovarian carcinoma (continued). "Our risk model, composed of six proteins (GSK3α/β, HSP70, MEK1, MTOR, BAD, and NDRG1), can predict survival of ovarian cancer patients effectively, thereby helping prognosis monitoring and decision making." (PMID 35840928, 2022). "The expression of the BAD-mediated apoptotic pathway phosphatase, PP2C, was evaluated by RT-qPCR in the normal and ovarian cancer tissue samples." (PMID 25653146, 2015). "The risk model composed of six proteins (GSK3α/β, HSP70, MEK1, MTOR, BAD, and NDRG1) could predict the survival prognosis of ovarian cancer efficiently and had a prominent predictive performance." (PMID 35840928, 2022). "Further work suggested that paclitaxel induces the phosphorylation of BAD Ser-112 via the Erk cascade, and the phosphorylation of both BAD Ser-136 and Raf-1 Ser-259 via the PI3K/Akt cascade, and that inhibition of either of these cascades sensitizes ovarian cancer cells to paclitaxel." (PMID 19384426, 2007).
glioma (10 papers, 2011 to 2025). A benign or malignant brain and spinal cord tumor that arises from glial cells (astrocytes, oligodendrocytes, ependymal cells). "Curiously, PI3K and phospho-AKT (Thr 308) have been implicated as distinguishing GBMs from lower grade gliomas, and phospho-BAD may be considered important in resistance to apoptosis." (PMID 27323862, 2016). "Our data suggest that the drug combination in our study induces apoptosis in glioma cell lines by decreasing Akt, downregulating Bcl-xL, and upregulating BAD." (PMID 36199696, 2022). "In particular, miR-126-3p and miR-182-5p were BAD-SPECIFIC miRNAs upregulated in both “Glioma” and “Proteoglycans in cancer” KEGG pathways, while miR-223-3p was exclusively upregulated in the second one." (PMID 33287106, 2020). "PPARγ agonists was able to up-regulate pro-apoptotic protein BAX and BAD expression, and then induced glioma cells apoptosis through releasing cytochrome C and activating the activation of caspase." (PMID 29642873, 2018). "Furthermore, molecules like Gefitinib is reported to induce apoptosis in human glioma by affecting the BAD/BAX signaling pathway including activating caspase 9/3." (PMID 39833890, 2025). "BAD and Bcl-2 are also potential target of wogonin in glioma." (PMID 36618921, 2022). "Then, considering the KEGG pathways “Glioma” and “Proteoglycans in cancer”, we evaluated how many miRNAs of each group (BAD-SPECIFIC and shared with GOOD) were involved, how many genes of the pathways could be modulated by upregulated or downregulated miRNAs, and the significance of the association." (PMID 33287106, 2020). "We further explored the genes, included in the “Glioma” and “Proteoglycans in cancer” KEGG pathways, regulated by miRNAs either BAD-SPECIFIC or EXO-SHARED." (PMID 33287106, 2020). "We found that IngC promoted modulation in proteins related to stress and cell cycle, as well as anti-apoptotic and pro-apoptotic protein expression, with special reduction in the levels of pro-apoptotic BAX, BAD, TNRI/TNFRSF1A, and FASTNFR6/CD95, were observed for most of glioma cell lines overtime." (PMID 31771098, 2019). "Substrates affected include FOXO transcription factors (FOXO3 and FOXO4) and BCL-2 protein family (BAD, BCL2, and BCL2L1) in which the phosphorylated state may ensure glioma cell survival under stressful environments." (PMID 21955618, 2011).
colon carcinoma (9 papers, 2015 to 2024). "The normal colon samples (n=10) had a mean BAD-mediated apoptotic pathway expression score of 4.049 vs. a value of −3.374 for the colon cancer samples (n=12; P<0.001)." (PMID 25653146, 2015). "A significant decrease of phosphorylated BAD at serine 112 is observed in pancreatic cancer Panc 28 and colon cancer CaCo-2 cells after treatment with flavone A. The activation of BAD at serine 112 is mediated by the MAPK pathway, specifically via the activation of Ras-Raf-ERK." (PMID 26606169, 2015). "In addition, TIMP1 could also increase anti-apoptosis of colon cancer in BAD mediated phosphoration pathway." (PMID 27644693, 2016). "We then treated cells with BAD, NOXA, PUMA, BMF, and HRK BH3 peptides, which have variable affinities for anti-apoptotic proteins, and compared the mitochondrial depolarization between parental and 5-FU-resistant colon cancer cells." (PMID 31638265, 2019).
gastric cancer (9 papers, 2016 to 2025). A primary or metastatic malignant neoplasm involving the stomach. "miR-BART20-5p was found to target apoptosis-inducing factor, Bcl2-associated agonist of cell death (BAD) and induce the proliferation of gastric cancer cells by repressing the expression of BAD." (PMID 28757548, 2017). "In AGS gastric cancer cells, we observed consistent 1.3-8-fold up-regulation of pro-apoptotic genes such as BAD, BAX, BID, and FAS after control lettuce and lettuce fortified with organic iodine, as compared to negative control." (PMID 36296971, 2022). "It has been found that EB virus miRNA miR-BART20-5p significantly increased 5-FU resistance of AGS1 gastric cancer cells by inhibiting BAD expression." (PMID 32192494, 2020). "In line with this, BAD phosphorylation promoted gastric cancer cell survival in response to growth factors." (PMID 30635657, 2019). "Here, we showed that purified HPU tested on three different gastric cancer epithelial cell lines increased their survival and inhibited apoptosis by modulation of the levels of Bcl-XL, an anti-apoptotic protein, and of BAD, a pro-apoptotic protein." (PMID 29021786, 2017). "Interestingly, Epstein-Barr (EB) virus miRNA miR-BART20-5p could also significantly increase ADR resistance of gastric cancer by inhibiting gene expression of BAD, a Bcl-2 family member." (PMID 32192494, 2020). "A study of miR-BART20-5p in Epstein-Barr virus-associated gastric carcinoma showed that miR-BART20-5p promotes the resistance of gastric carcinoma cell line AGS to 5-FU and docetaxel by downregulating the BAD expression." (PMID 34912714, 2021).
colorectal cancer (8 papers, 2013 to 2025). A primary or metastatic malignant neoplasm that affects the colon or rectum. "The reduction of BAD protein expression by RNA interference rescued colorectal cancer cells from THC-induced apoptosis." (PMID 40804975, 2025). "For example, the expression level of four genes, such as BAD, decreased in colorectal cancer, while the expression level of 28 genes, such as STMN1, increased in colorectal cancer." (PMID 38528462, 2024). "There was a positive correlation between overexpression of phospho-BAD and phosphorylated Akt in colorectal carcinoma." (PMID 26398947, 2015). "We examined the IGF-1R downstream AKT and ERK growth pathways and BAD-mediated mitochondrial apoptotic pathway in PPP-treated colorectal carcinoma cells." (PMID 24182354, 2013). "By activating PI3K/AKT and ERK growth pathways and inhibiting the BAD and TNFα-mediated apoptosis, the IGF-1R signaling pathway promotes the survival, growth, and metastasis of colorectal carcinomas." (PMID 24182354, 2013). "Considering that the in vitro results of STMN1 and BAD in colorectal treatment were inconsistent, our results suggested that Fenticonazole may not provide a new therapeutic action in colorectal cancer and that it needed more research to be introduced as an anti-cancer drug." (PMID 38528462, 2024).
breast tumors (7 papers, 2010 to 2019). "Thus, BAD increases breast tumor growth through two distinct pathways that can be differentiated by dependence on S118 phosphorylation." (PMID 30635657, 2019). "In contrast, other breast tumors appeared statistically enriched for two PMAIP1 (Noxa) specific probes and for one BAD specific one." (PMID 21899728, 2011). "Conversely, sustained BAD-LAMP expression in pDCs contributes to their lack of type I interferon production after exposure to a TGF-β-positive microenvironment or isolation from human breast tumours." (PMID 29030552, 2017).
lymphoma (7 papers, 2012 to 2023). A malignant (clonal) proliferation of B- lymphocytes or T- lymphocytes which involves the lymph nodes, bone marrow and/or extranodal sites. "Besides, it has been reported that BAD suppresses the formation of tumors in lymphocytes and that Bad-deficient mice are at higher risk of lymphoma and leukemia." (PMID 29126409, 2017). "Disruption of pro-apoptotic BCL2 family genes [e.g., BAD, BIM, BMF, PUMA] also accelerates lymphoma development in the Eμ-myc model." (PMID 33651821, 2021). "Both PI-103 & quercetin suppressed the enhanced level of ROS and significantly down-regulated phosphorylation of AKT, PDK1, BAD and level of TNFR1 as well as increased the level of PTEN in H2O2 induced lymphoma cells." (PMID 27494022, 2016).
Hyperglycemia (6 papers, 2011 to 2024). An increased concentration of glucose in the blood. "Hyperglycemia/glucotoxic stress increased BAD protein expression in human and mouse pancreatic islets and caused β-cell death." (PMID 26351642, 2015). "However, in H9c2 cardiomyoblasts exposed to chronic hyperglycaemia, excessive O-GlcNAcylation of the proapoptotic protein BAD has been shown to contribute to the formation of the BAD-Bcl-2 dimer, thus enhancing cellular apoptosis." (PMID 38491477, 2024). "For example, enhanced Ca2+ entry concomitant with hyperglycemia may also activate the calcium-dependent phosphatase calcineurin, leading to the dephosphorylation of the pro-apoptotic protein BAD that facilitates apoptosis in other cells." (PMID 23049237, 2012). "Thus, a reduced phosphorylation of BAD in the diabetic pancreas is consistent with an increased apoptosis in type 2 diabetes that possibly occurs, in part, secondary to hyperglycemia." (PMID 22140505, 2011).
leukemia (6 papers, 2017 to 2023). A malignant (clonal) hematologic disorder, involving hematopoietic stem cells and characterized by the presence of primitive or atypical myeloid or lymphoid cells in the bone marrow and the blood. "Interestingly, functional dependence of the leukemia cells on BCL-2 (BAD-HRK priming) was strongly associated with in vivo VEN activity, and importantly, showed high sensitivity and specificity in predicting preclinical in vivo antileukemia activity of VEN." (PMID 31358732, 2019). "Thus, a strong functional dependence of the leukemia cell on BCL-2 (BAD-HRK priming) is highly indicative for ex vivo anti-ALL activity of VEN." (PMID 31358732, 2019).
cervical cancer (5 papers, 2011 to 2022). A primary or metastatic malignant neoplasm involving the cervix. "Our results showed that kin17 knockdown increased the expression of proapoptotic Bim and decreased the expression of antiapoptotic Bcl-xL and phosphorylated BAD in cervical cancer." (PMID 35909901, 2022). "PA-MSHA induced BAD and BAX and inhibited BCL-2, suggesting that PA-MSHA promotes apoptosis in cervical cancer cells by increasing the expression of pro-apoptotic genes and reducing the expression of anti-apoptotic genes." (PMID 27206797, 2016).
endometrial cancer (5 papers, 2013 to 2022). Primary or metastatic malignant neoplasm involving the endometrium (mucous membrane that lines the endometrial cavity). "We and others have demonstrated that the expression of the BAD-mediated apoptotic pathway and the phosphorylation status of the BAD protein influence the chemosensitivity of cancer cells, including ovarian and endometrial cancer cells." (PMID 25653146, 2015). "Common genetic variants in the BCL-2-family genes BCL2, BAD, BAX and BAK1 were comprehensively evaluated for associations with endometrial cancer risk." (PMID 23637776, 2013). "We investigated whether genetic variants in the BCL-2-family genes BAD, BAX, BCL2 or BAK1 are associated with endometrial cancer risk." (PMID 23637776, 2013). "Ectopic expression of LRIG2 downregulated the pro-survival BCL-2 family members, including MCL-1, BCL-xL, BCL2A1, and BCL-2, whereas the pro-apoptotic BCL-2 family members, such as BAK, BAX, and BAD, were upregulated by LRIG2 in endometrial cancer cells." (PMID 29358688, 2018).
pancreatic cancer (5 papers, 2009 to 2022). "Apoptosis-associated proteins Bax, Bcl-2, BAD and survivin have all been demonstrated to be involved in the chemoresistance of pancreatic cancer cells and be regulated by FAK or Akt." (PMID 20021699, 2009). "The results of flow cytometry and Western blot showed that wogonin may enhance the sensitivity of pancreatic cancer cells to gemcitabine by inhibiting p-Akt, anti-apoptotic gene Bcl-2, activating pro-apoptotic gene BAD, and promoting apoptosis of Panc-1." (PMID 36618921, 2022). "In turn, the observed reduction in AKT activation might lead to BAD-induced apoptosis of rHDL1-treated pancreatic-cancer cells." (PMID 35577388, 2022). "Therefore, we examined the change in BAD phosphorylation in CXCL12-treated pancreatic cancer cells." (PMID 21045835, 2010). "Our data showed an increased level of phospho-BAD in both Panc1 and MiaPaCa cell lines treated with CXCL12, suggesting that it could be one of the mechanisms by which CXCL12–CXCR4 signalling axis protects the pancreatic cancer cells from apoptosis." (PMID 21045835, 2010).
prostate tumors (5 papers, 2009 to 2019). "This connection between BAD expression and proliferation provides a possible explanation for an increase in expression of phosphorylated BAD protein in prostate tumors." (PMID 19593445, 2009). "Knockout of BAD diminished the suppressive effect of n-3 PUFA on prostate tumor growth in vivo." (PMID 23762859, 2013). "To determine whether increased expression levels of BAD stimulate prostate tumor growth in vivo, we compared growth of C4-2Luc and C4-2LucBAD cells implanted in immunocompromised mice." (PMID 19593445, 2009). "It is possible that in addition to regulating apoptosis, BAD might play a positive role in prostatic tumor growth." (PMID 19593445, 2009). "The results showed that the mRNA levels of BAD, CCND2 and PDGF-D were differentially expressed in prostate tumor tissues and normal prostate gland." (PMID 28674394, 2017). "We, therefore, asked whether induced Akt activation in response to ENZ could inactivate BAD, resulting in a BCLxL‐mediated apoptosis evasion mechanism in PTEN‐wild‐type prostate tumor cells." (PMID 31228231, 2019). "Both BAD and MCL-1 are ubiquitously expressed in prostate tumors and could be dynamically regulated by phosphorylation (in the case of BAD) and both phosphorylation and ubiquitylation (in the case of MCL-1)." (PMID 24040284, 2013).
Acute Myeloid Leukaemia (4 papers, 2010 to 2022). "We determined the applicability of the BAD/NOXA co-operating interaction to two novel chemotherapeutic compounds, TG02 and ABT-199, in Acute Myeloid Leukaemia." (PMID 27092880, 2017). "In THP-1 acute myeloid leukaemia cells, there was a significant decrease in the expression of BCL2, BCLX, and BAD genes and proteins; with a significant increase in TNFR1/TNFRSF1A, CASP-9, and CASP-3 gene expression, when compared to the vehicle control (P ≤ 0.05)." (PMID 35614109, 2022).